MLF2 (myeloid leukemia factor 2)
Synonyms: NTN4
Tractability: Antibody: the Human Protein Atlas places it where antibodies can reach. PROTAC: its protein half-life has been measured.
Gene: Protein-coding gene on chromosome 12 (6,747,986 to 6,768,932, reverse strand). Ensembl gene ENSG00000089693.
Subcellular location: Cytoplasm; Nucleus
Subcellular location (Human Protein Atlas): Nucleoplasm; Cytosol; Plasma membrane
Gene Ontology:
Molecular function: protein binding
Biological process: regulation of DNA-templated transcription
Cellular component: membrane; cytoplasm; nucleus; glutamatergic synapse; synapse
Genetic constraint (gnomAD): Loss-of-function variants: 12 observed, 29.98 expected, observed/expected ratio (o/e) 0.4, 90% interval 0.25 to 0.65. The upper end of that interval is the gene's LOEUF score, 0.65, which puts it in group 2 of 6, group 1 being the genes least tolerant of losing a copy. Missense variants: 272 observed, 360.4 expected, observed/expected ratio (o/e) 0.75, 90% interval 0.68 to 0.83. Synonymous variants: 109 observed, 120.11 expected, observed/expected ratio (o/e) 0.91, 90% interval 0.78 to 1.06.
Homologues: Orthologues: macaque MLF2 (100% identical), dog MLF2 (98% identical), guinea pig MLF2 (98% identical), mouse Mlf2 (97% identical), rat Mlf2 (97% identical), pig MLF2 (93% identical), chimpanzee MLF2 (90% identical), tropical clawed frog mlf2 (68% identical), zebrafish mlf2 (57% identical), Drosophila melanogaster Mlf (31% identical), Caenorhabditis elegans Y17G7B.17 (28% identical). Paralogues in human: MLF1 (40% identical).
Diseases named in the same sentence as MLF2 in open-access papers:
MLF2 is named in the same sentence as 25 diseases in open-access papers, as found by Europe PMC text mining. Sharing a sentence is not in itself a finding about the gene and the disease. The quoted sentences say what the papers report.
breast carcinoma (5 papers, 2020 to 2023). "Mechanistically, RPL39 and MLF2 expression was associated with iNOS signaling, and their mutations were associated with shorter median time to relapse in a cohort of 53 breast cancer patients, which suggests that iNOS inhibition represents a promising strategy for the treatment of TNBC." (PMID 33138097, 2020). "Targeting RPL39 and MLF2 reduces tumor initiation and metastasis in breast cancer by inhibiting nitric oxide synthase signaling." (PMID 34497807, 2021). "A more interesting study identified two previously unidentified cancer genes, RPL39 and MLF2, by selective shRNA knockdown of genes from this tumorigenic signature, which impacted breast cancer stem cell self-renewal and lung metastases." (PMID 34497807, 2021). "Although recent evidence suggests a potential oncogenic role of MLF2 in breast cancer and chronic myelogenous leukemia, it remains unclear how MLF2 is involved in tumorigenesis." (PMID 37438558, 2023). "Interestingly, previous studies have shown that the suppression of a myeloid leukemia factor (MLF2), an oncogene in breast cancer and myeloid leukemia as well as UBTF which controls rDNA expression contributes significantly to cancers upon promoter hypermethylation." (PMID 34557292, 2021).
Huntington disease (3 papers, 2017 to 2025). Huntington disease (HD) is a rare neurodegenerative disorder of the central nervous system characterized by unwanted choreatic movements, behavioral and psychiatric disturbances and dementia. "The protein aggregates formed in Huntington’s disease were shown to contain Mlf1, but overexpression of Mlf1 or Mlf2 leads to the release of proteins from these aggregates." (PMID 39432513, 2024).
Desminopathy (2 papers, 2025). "Notably, Mlf2, an interaction partner of Mlf1, has been shown be enriched in protein aggregates in human desminopathies thus highlighting a novel and conceivable disease link between Mlf1 and Mlf2 related transcriptional control and Dnajb6 and Bag3 mediated protein quality control." (PMID 41165044, 2025).
acute leukemia (1 paper, 2010). A clonal (malignant) hematopoietic disorder with an acute onset, affecting the bone marrow and the peripheral blood. "Similarly to MLF1, the chromosomal translocations and deletions of myeloid leukemia factor 2 (MLF2) locus were also observed in acute leukemia, but no direct studies were performed to identify the specific mechanism of its action." (PMID 20633251, 2010).
cardiac hypertrophy (1 paper, 2025). "Supporting this notion, we observed that MLF1 overexpression downregulated MLF2 expression, and vice versa, indicating an inverse regulation that may have functional relevance in the context of cardiac hypertrophy." (PMID 41590846, 2025). "These opposing effects suggest that MLF1 and MLF2 may have antagonistic roles in cardiac hypertrophy." (PMID 41590846, 2025).
cardiomyopathies (1 paper, 2025). "Across multiple mouse models of desmin-related cardiomyopathies, MLF2 was consistently enriched in protein aggregates and interacted with key proteins involved in protein quality control, including αB-crystallin (CryAB)." (PMID 41590846, 2025).
coccidiosis (1 paper, 2011). A parasitic infection caused by Coccidia. "In this study allele substitution effect analysis and classification of MLF2 haplotype elucidated parental origin of haplotype associated with coccidiosis resistance." (PMID 21645301, 2011). "Allele substitution effect of the MLF2 haplotype originated from a specific line was associated with increased body weight and fecal egg count explaining coccidiosis resistance." (PMID 21645301, 2011). "Allele substitution effect analysis and classification of MLF2 haplotype identified the segregation of haplotype associated with coccidiosis resistance." (PMID 21645301, 2011). "Thus, this study was suggested to identify segregation of MLF2 allele associated with coccidiosis resistance for practical application and future study for identifying causative mutation." (PMID 21645301, 2011). "MLF2 was the candidate gene associated with coccidiosis resistance in chickens." (PMID 21645301, 2011). "Associations between parameters of resistance to coccidiosis and single nucleotide polymorphisms (SNPs) in 3 candidate genes located around QTL on chromosome 1 (Zyxin, TCR-β, MLF2) were determined." (PMID 21645301, 2011). "Estimating effect of MLF2 haplotype on coccidiosis resistance will provide useful information for selecting animals or lines for future study." (PMID 21645301, 2011). "Single marker association analysis for 16 traits of coccidiosis resistance showed SNPs of TCR-β and MLF2 were associated with oocyst shedding and body weights in previous study, and it was confirmed by additional association tests in current study." (PMID 21645301, 2011). "Although single marker analysis supported the association between MLF2 and coccidiosis resistance, causative mutation relevant to coccidiosis was not identified yet." (PMID 21645301, 2011).
colorectal adenocarcinoma (1 paper, 2023). The most common type of colorectal carcinoma. "Moreover, colorectal adenocarcinoma patients with high MLF2 expression had a shorter overall survival than those with low MLF2 expression." (PMID 37438558, 2023). "In addition, colorectal adenocarcinoma patients with a higher expression of MLF2 had a higher clinical stage, indicating that the expression levels of MLF2 are positively correlated with the clinical stage of colorectal adenocarcinoma." (PMID 37438558, 2023).
colorectal cancer (1 paper, 2023). A primary or metastatic malignant neoplasm that affects the colon or rectum. "Clinically, MLF2 is elevated in colorectal cancer and its high expression is associated with poor prognosis in patients with colorectal cancer." (PMID 37438558, 2023). "Moreover, MLF2 is overexpressed in clinical colorectal cancer specimens and high MLF2 expression is associated with reduced patient survival." (PMID 37438558, 2023). "We first evaluated the effect of MLF2 on cell proliferation and apoptosis in the colorectal cancer cell lines HCT116 and RKO." (PMID 37438558, 2023). "Meanwhile, MLF2 is highly expressed in colorectal cancer and the expression of MLF2 is negatively correlated with patient survival." (PMID 37438558, 2023).
cyst (1 paper, 2023). A sac-like closed membranous structure that may be empty or contain fluid or amorphous material. "To understand MLF function change in evolution, we tested whether human MLF2 had similar inducing effect with Giardia MLF on cyst differentiation." (PMID 37095576, 2023). "Furthermore, human MLF2, like Giardia MLF, can increase cyst wall protein expression and cyst formation in G. lamblia, and it can colocalize with MLFVs and interact with MLF." (PMID 37095576, 2023).
dilated cardiomyopathy (1 paper, 2025). Cardiomyopathy which is characterized by dilation and contractile dysfunction of the left and right ventricles. "A transcriptomic study identified MLF2 as a potential biomarker for dilated cardiomyopathy (DCM)." (PMID 41590846, 2025). "In this context, myeloid leukaemia factor 2 (MLF2) emerged as a candidate of interest, as we found it overrepresented in protein aggregates in the hearts of mouse models of desmin-related cardiomyopathies (DRM), and it has also been suggested to be associated with dilated cardiomyopathy (DCM)." (PMID 41590846, 2025).
heart failure (1 paper, 2025). Inability of the heart to pump blood at an adequate rate to meet tissue metabolic requirements. "Functionally, MLF2 was significantly upregulated in mouse models of heart failure and in two in vitro models of cardiomyocyte hypertrophy, and its overexpression resulted in attenuation of pro-hypertrophic gene expression." (PMID 41590846, 2025). "We demonstrate that MLF2 is significantly upregulated in a mouse model of pressure overload–induced heart failure, as well as in two in vitro models of cardiomyocyte hypertrophy." (PMID 41590846, 2025).
cancer (7 papers, 2015 to 2025). A tumor composed of atypical neoplastic, often pleomorphic cells that invade other tissues. "Despite these intriguing observations linking MLF2 to cancer biology, DRM and DCM, its specific role in cardiomyocytes remains poorly understood." (PMID 41590846, 2025). "Early research on both proteins focused largely on their roles in malignant tumours: MLF2 overexpression enhances survival of various tumour cell lines, whereas MLF2 downregulation reduces tumour initiation and metastasis." (PMID 41590846, 2025). "Beyond its role in cancer biology, MLF2 has recently gained attention in cardiac research." (PMID 41590846, 2025). "More interestingly, seven different genes (ECH1, PEX5, MLF2, NFIX, TSPAN9, SAMD4B, and NFKBIB) were associated with another drug C646, which is a small molecule inhibitor targeting histone acetyltransferase p300, an enzyme that alters the cancer transcriptome in the lung, colon and pancreas." (PMID 29207666, 2017). "Among these, MLF2, COPS7A, PEX5, DDX47, STRAP and MRPL51 displayed strong correlations with USP5 in most cancer types." (PMID 37268697, 2023). "We have recently described two novel cancer genes (RPL39 and MLF2) that are important for tumor initiation and metastasis and are regulated by the NO signaling pathway." (PMID 25849745, 2015).
tumor (7 papers, 2015 to 2025). "And in non-progression group, copy number deletion contributing to low expression of MLF2 has been reported to inhibit tumor metastasis." (PMID 35022521, 2022).
cardiac diseases (1 paper, 2025). "To investigate a potential influence of MLF2 on cardiac disorders, we further explored the role of MLF2 in cardiac disease models." (PMID 41590846, 2025). "We show that MLF2, identified in protein aggregates across cardiac and non-cardiac disease models, interacts with proteins involved in proteostasis, including CryAB." (PMID 41590846, 2025). "In addition, MLF2 has been shown to colocalise to protein aggregates in other non-cardiac diseases and disease models with pathological protein deposition." (PMID 41590846, 2025).
colorectal (1 paper, 2023).
myopathy (1 paper, 2022). A disease of the muscle in which the muscle fibers do not function properly. "Forty-six candidate genes are prioritized by multiple approaches (42 for LST and 6 for MVPA; 2 overlap) and point to endocytosis (CNIH2, RAB1B, KLC2, PACS1, REPS1, DNM3, EXOC4), locomotion (CADM2, KLC2) and myopathy (MLF2, HERC1, KLC2, SIL1) as relevant pathways." (PMID 36071172, 2022).
MLF2 also shares sentences with these, for which no sentence is quoted: chronic myelogenous leukemia (2 papers); acute myeloid leukemia (1); amyotrophic lateral sclerosis (1); filaminopathy (1); frontotemporal dementia (1); leukemia (1); movement disorder (1); myelodysplastic syndrome (1).